HOTAIR (HOX transcript antisense RNA)
Diseases named in the same sentence as HOTAIR in open-access papers (continued):
Sharing a sentence is not in itself a finding about the gene and the disease.
esophageal cancer (28 papers, 2014 to 2025). A primary or metastatic malignant neoplasm involving the esophagus. "HOTAIR rs920778 contributed to the increased risk of esophageal cancer in all models (dominant model: 1.48, 1.31-1.67; recessive model: 2.51, 1.91-3.29; additive model: 1.48, 1.34-1.64)." (PMID 28159929, 2017). "For esophageal carcinoma, high HOTAIR expression was significantly associated with TNM stage (III/IV vs. I/II: OR 6.90, 95% CI: 2.81–16.9) without heterogeneity." (PMID 25157956, 2014). "We found that high HOTAIR expression in esophageal carcinoma was significantly associated with TNM stage (III/IV vs. I/II: OR 6.90, 95%CI: 2.81–16.9) without obvious heterogeneity." (PMID 25157956, 2014). "Taken together, the results obtained indicate that the down‐regulation of HOTAIR can suppress oesophageal cancer cell tumourigenicity through the up‐regulation of miR‐204." (PMID 31389660, 2019). "Considering the mechanism by which IL‐11 influences cancer has been thoroughly studied, we aimed to investigate the mechanism by which HOTAIR acting as a ceRNA of miR‐204 regulates the expression of HOXC8 in oesophageal cancer cells." (PMID 31389660, 2019). "Immunohistochemistry and RT‐qPCR were conducted in order to determine the expression pattern of HOXC8, HOTAIR and miR‐204 in the oesophageal cancer tissues as well as the adjacent normal tissues." (PMID 31389660, 2019). "Our results revealed that miR‐204 was poorly expressed in the oesophageal cancer tissues while HOTAIR and HOXC8 were highly expressed." (PMID 31389660, 2019). "The functions of HOTAIR and miR‐204 on the viability of oesophageal cancer cells were examined through the application of a MTT assay." (PMID 31389660, 2019). "Silenced HOTAIR or elevated miR‐204 inhibited proliferation, migration and invasion, along with stimulated apoptosis of oesophageal cancer cells." (PMID 31389660, 2019). "The endogenous expression of HOTAIR and miR‐204 in oesophageal cancer cell lines was altered to elucidate their effects and to identify the interaction among HOTAIR, miR‐204 and HOXC8." (PMID 31389660, 2019). "lncRNAs (AFAP1-AS1, UCA1, HOTAIR) were found to be dysregulated in cisplatin-resistant esophageal cancer cells compared with the corresponding parent cells." (PMID 28388588, 2017). "In esophageal cancer, HOTAIR promotes the EMT and enhances metastasis by sponging miRNA-148a to regulate Sail2." (PMID 29156804, 2017). "HOTAIR promoted activation of the Wnt/β-catenin pathway in esophageal carcinoma, so β-catenin can link HOTAIR, MMPs, and autophagy in cancer." (PMID 29469819, 2017). "We extended this analysis to reported HOTAIR target genes in pancreatic and esophageal cancer cells." (PMID 25994132, 2015). "Furthermore, HOTAIR can be transferred between cells via extracellular vesicles (EVs), as observed in esophageal cancer, where EV-delivered HOTAIR modulates the TME and upregulates PD-L1 in recipient cells, contributing to chemoresistance and immune escape." (PMID 41221298, 2025). "Hence, we explored the contribution of four long non-coding RNAs’ polymorphisms HOTAIR rs920778, LINC00951 rs11752942, POLR2E rs3787016 and HULC rs7763881 in esophageal cancer susceptibility." (PMID 38300349, 2024). "HOTAIR rs920778 may serve as a potential therapeutic suppression target, while POLR2E rs3787016 may represent a valuable biomarker to evaluate esophageal cancer predisposition and predict treatment response and prognosis." (PMID 38300349, 2024). "Meanwhile, xenografts from HOTAIR-silenced esophageal cancer cells in nude mice also demonstrated the diminished 5-FU resistance, indicating that HOTAIR may represent a novel potential target for conquering 5-FU resistance of esophageal cancer." (PMID 34881242, 2021). "A number of esophageal cancer-related lncRNAs were dysregulated in obesity such as ANRIL, H19, and HOTAIR, suggesting that obesity-associated lncRNAs may promote development of cancer." (PMID 32133283, 2020).
esophageal cancer (continued). "This suggested that repression of HOTAIR could be clinically helpful to suppress oesophageal cancer progression and HOTAIR could be a promising target for oesophageal cancer treatment." (PMID 31389660, 2019). "Our results further highlighted that the down‐regulation of HOTAIR could inhibit proliferation, invasion and migration, while acting to suppress the apoptosis of oesophageal cancer cell lines and inhibit the tumour formation in nude mice through the up‐regulation of miR‐204." (PMID 31389660, 2019). "Hence, down‐regulation of HOTAIR could inhibit progression of oesophageal cancer, indicating a novel target for oesophageal cancer treatment." (PMID 31389660, 2019). "In the present study, 10 lncRNAs (HOTAIR, AFAP1-AS1, POU3F3, HNF1A-AS1, 91H, PlncRNA1, SPRY4-IT1, ENST00000435885.1, XLOC_013104 and ENST00000547963.1) that were previously reported with deregulated expression in esophageal cancer were selected as candidate diagnostic makers." (PMID 25608466, 2015). "Dysregulated lncRNAs, such as UCA1, HOTAIR, and TUG1, have been proposed as prognostic biomarkers for esophageal cancer." (PMID 35619131, 2022). "Consistent with our findings, HOTAIR positively regulated snail expression by sponging miR‐148a thereby enhancing cell invasion and metastasis and promote the EMT in oesophageal cancer was reported." (PMID 32248643, 2020). "Herein, we tried to demonstrate the function of HOTAIR, miR‐204 and HOXC8 in oesophageal cancer and their relationship." (PMID 31389660, 2019). "miR‐204 was down‐regulated, while HOTAIR and HOXC8 were up‐regulated in the oesophageal cancer tissues." (PMID 31389660, 2019). "HOTAIR acts as a miR-148a sponge and positively regulates Snail2 expression, which promotes cell invasion, metastasis and EMT in esophageal cancer." (PMID 29132362, 2017). "In esophageal cancer patients, long non-coding RNA HOTAIR (HOX transcript antisense RNA) has been found up-regulated and critical for esophageal cancer cell metastasis in nude mice." (PMID 25606572, 2014). "Silencing of HOTAIR could promote the apoptosis induced by 5-FU and alleviate cell proliferation and MTHFR promoter methylation of esophageal cancer cells." (PMID 34881242, 2021). "To conclude, this study illustrated that lncRNA HOTAIR could function as a ceRNA of miR‐204, and the silencing of HOTAIR could reduce expression of HOXC8, which ultimately inhibited the proliferation, migration and invasion of oesophageal cancer cells." (PMID 31389660, 2019). "Thus, silencing of HOTAIR could suppress the expression of HOXC8 via miR‐204 and inhibit proliferation, migration and invasion while inducing apoptosis of oesophageal cancer cells." (PMID 31389660, 2019). "HOTAIR overexpression was correlated with short survival in esophageal cancer regardless of the ethnicities, indicating that high HOTAIR level may be a prognostic factor for esophageal cancer." (PMID 28388588, 2017). "On the basis of previous study, 10 lncRNAs (HOTAIR, AFAP1-AS1, POU3F3, HNF1A-AS1, PlncRNA1, SPRY4-IT1, ENST00000435885.1, ENST00000547963.1, 91H and XLOC_013104) which have been reported to be differently expressed in esophageal cancer were selected in the present study." (PMID 25608466, 2015). "Ten lncRNAs (HOTAIR, AFAP1-AS1, POU3F3, HNF1A-AS1, 91H, PlncRNA1, SPRY4-IT1, ENST00000435885.1, XLOC_013104 and ENST00000547963.1) which previously found to be differently expressed in esophageal cancer were selected as candidate targets for subsequent circulating lncRNA assay." (PMID 25608466, 2015).
osteosarcoma (28 papers, 2016 to 2025). A usually aggressive malignant bone-forming mesenchymal neoplasm, predominantly affecting adolescents and young adults. "In an study on osteosarcoma patients classified by age, gender, and tumor locations, it was shown that CC genotypes of the HOTAIR rs7958904 can reduce osteosarcoma risk as well as HOTAIR expression level." (PMID 30873206, 2019). "For example, the knockdown of HOTAIR in cisplatin-resistant osteosarcoma cells and tissue led to reduced expression of drug resistance-related genes and decreased resistance to cisplatin, suppressed cell proliferation and invasion, and enhanced apoptosis." (PMID 38256203, 2024). "Since then, an enormous number of studies have been published that demonstrate abnormal expression of HOTAIR in various tumor types, among them, endometrial, lung, osteosarcoma, ovarian, and oral cancer." (PMID 38256203, 2024). "The growth of osteosarcoma can be inhibited in U20S cells with HOTAIR knockdown following implantation in xenograft models." (PMID 39015175, 2024). "HOTAIR repressed the progression of osteosarcoma via regulating LPR5 and suppressing the Wnt/β-cadherin pathway." (PMID 36816362, 2023). "Downregulation of HOTAIR was detected in osteosarcoma, which predicted poor prognosis of patients with osteosarcoma." (PMID 36816362, 2023). "In osteosarcoma, HOTAIR was found to positively regulate the global DNA methylation level and specifically DNMT1 expression, making it an interesting diagnostic marker and therapeutic target." (PMID 35755302, 2022). "HOTAIR was overexpressed in cisplatin (DDP)-resistant osteosarcoma cells and tissues and enhanced DDP resistance of osteosarcoma cells through the miR-106a-5p/STAT3 axis." (PMID 34367966, 2021). "ZEB1 was identified as a downstream gene of miR-217, suggesting that HOTAIR can mediate osteosarcoma progression by upregulating ZEB1 expression via acting as a competitive endogenous RNA (ceRNA) via miR-217." (PMID 34576322, 2021). "Many studies are focused on osteosarcoma (OS), highlighting the main role of HOTAIR as prognostic biomarker." (PMID 34576322, 2021). "HOTAIR expression markedly increases in LPS-induced EMT in osteosarcoma cells, such as TLR4 (Toll Like Receptor 4), which is the LPS receptor, suggesting that the effects of LPS on EMT in osteosarcoma cells is mediated via the TLR4/HOTAIR pathway." (PMID 34576322, 2021). "With regard to osteosarcoma, lncRNAs such as HOTAIR, HULC, H19 and MALAT-1, have been identified to be aberrantly expressed in cancer and function with underlying mechanisms." (PMID 31443665, 2019). "For example, in osteosarcoma, lncRNAs HOTAIR, SNHG16, SNHG12, THOR, PACER, MFI2, and HOTTIP have all been shown to promote tumor or cell growth." (PMID 31616462, 2019). "Compared with normal tissue, the expression level of HOTAIR was significantly higher in osteosarcoma patients." (PMID 28353666, 2017). "HOTAIR can promote the proliferation and inhibit the apoptosis of MG-63 cells in vitro and can be a potential target for the treatment of osteosarcoma." (PMID 27660759, 2016). "HOTAIR was highly expressed in osteosarcoma MG-63 cell line compared with normal osteoblast hFOB1.19 cell line." (PMID 27660759, 2016). "We found that HOTAIR was highly expressed in osteosarcoma MG-63 cell line compared with normal osteoblast hFOB1.19 cell line." (PMID 27660759, 2016). "This study aimed to explore the function of HOTAIR in osteosarcoma." (PMID 36816362, 2023). "Our findings will provide a positive reference for studying the function of HOTAIR in osteosarcoma." (PMID 36816362, 2023). "Moreover, cell migration, invasion, and proliferation were suppressed by HOTAIR overexpression in osteosarcoma." (PMID 36816362, 2023). "Therefore, the lncRNAHOTAIR-miR126-DNMT1-CDKN2A axis was proposed to be a novel therapeutic alternative, especially targeting HOTAIR due to its potential to increase osteosarcoma chemosensitivity toward DNMT1 inhibitors." (PMID 35755302, 2022).
osteosarcoma (continued). "During osteosarcoma progression, HOTAIR may act as a sponge for miR-217, involved in the repression of growth, migration, and invasion of osteosarcoma cells." (PMID 33540611, 2021). "In osteosarcoma samples, HOTAIR was commonly over-expressed." (PMID 28353666, 2017). "For OS, HOTAIR was only reported such that overexpression of HOTAIR could promote tumor growth and metastasis in human osteosarcoma." (PMID 27660759, 2016). "Furthermore, LPR5 was a direct target of HOTAIR, which was upregulated in osteosarcoma." (PMID 36816362, 2023). "HOTAIR could be a potential target for the treatment of osteosarcoma." (PMID 27660759, 2016). "These included lncRNAs TUG1, HOTAIR and UCA1 which were slightly elevated in lung metastatic osteosarcomas." (PMID 32728178, 2020). "In retinoblastoma, HOTAIR, THOR, and MEG3 appear to have a similar influence as seen in osteosarcoma, where they also acted as oncogenes (HOTAIR and THOR) or tumor suppressors (MEG3)." (PMID 31616462, 2019). "Nine different long non-coding RNAs were studied in these 10 included articles, with 7 lncRNAs including MALAT1, BCAR4, FGFR3-AS1, HOTAIR, TUG1, FOXC2-AS1 and PVT1 were up-regulated in osteosarcoma cells or patients." (PMID 29245999, 2017). "HOTAIR was found to negatively regulate the EMT and Wnt/β-cadherin pathways in osteosarcoma." (PMID 36816362, 2023). "HOTAIR is commonly overexpressed in osteosarcoma, and its knockdown significantly inhibits cellular proliferation and invasion by decreasing MMP-2 and MMP-9 section in osteosarcoma cells." (PMID 27685633, 2016). "However, the role of HOTAIR was not reported in osteosarcoma." (PMID 36816362, 2023).
bladder cancer (27 papers, 2015 to 2025). "Despite numerous studies exploring the functional and prognostic relevance of HOTAIR in bladder cancer, research on HOTAIR single-nucleotide polymorphisms (SNPs) remains limited." (PMID 38275875, 2024). "In this study, we evaluated the impact of the HOTAIR single nucleotide polymorphisms rs920778 and rs12826786 on bladder cancer risk and survival." (PMID 38275875, 2024). "The aim of this study was to determine the relevance of the HOTAIR rs920778 and rs12826786 genetic variants in bladder cancer susceptibility and prognosis." (PMID 38275875, 2024). "HOTAIR expression was shown to be associated with prognosis, and poor disease-free survival in bladder cancer." (PMID 36685879, 2022). "Further, the aberrant expression of HOTAIR was associated with poor disease-free survival of bladder cancer." (PMID 34367966, 2021). "Clinically, there are many types of lncRNA associated with bladder cancer, including HOTAIR, MALAT1, H19, etc., all of which play an important role in the occurrence and development of bladder cancer." (PMID 33898446, 2021). "For example, H19 is aberrantly expressed in many types of cancer such as liver and bladder cancers and pancreatic ductal carcinoma, while HOTAIR has been implicated in various aspects of cancer development." (PMID 27604105, 2017). "This case-control study, comprising 106 Portuguese bladder cancer patients and 199 cancer-free control individuals, focused on exploiting the relevance of two genetic variants of HOTAIR—an acknowledged oncogenic molecule in bladder cancer —in the risk and prognosis of bladder cancer patients." (PMID 38275875, 2024). "Initially, we conducted univariable analyses to examine whether specific variants of these HOTAIR polymorphisms were associated with bladder cancer risk." (PMID 38275875, 2024). "Nevertheless, survival analyses suggested that the HOTAIR rs920778 TT genotype and rs12826786 CC genotype are associated with increased survival in male bladder cancer patients and in patients, both male and female, who have primary tumors with a pathological stage of pT2." (PMID 38275875, 2024). "Beyond its prognostic significance, HOTAIR might also hold diagnostic importance in bladder cancer, as it is enriched in exosomes isolated from the urine samples of patients diagnosed with muscle-invasive high-grade urothelial bladder cancer." (PMID 38275875, 2024). "However, the mechanism underlying the role of HOTAIR in the resistance to cisplatin in bladder cancer is unclear." (PMID 36471329, 2022). "It is reported that the level of lncRNA HOTAIR increases in cachexia induced by bladder cancer, and inhibition of lncRNA HOTAIR can decelerate cachectic progress." (PMID 39404384, 2024). "In this study we focused on HOTAIR, not only for its known relevance in bladder cancer, but also for its critical role in other cancer types." (PMID 38275875, 2024). "The frequencies of TT, CC, and CT for HOTAIR rs920778 were 45.2, 12.6, and 42.2% for the cancer-free individuals, and 46.2, 13.2, and 40.6% for the bladder cancer patients." (PMID 38275875, 2024). "Our findings reveal that specific groups of patients (male patients and pT2 bladder cancer patients) carrying the TT genotype in HOTAIR rs920778 have significantly longer overall survival." (PMID 38275875, 2024). "Considering that the high expression of HOTAIR is a predictor of shorter survival in bladder cancer patients, we also explored the potential effects of the HOTAIR rs920778 and rs12826786 SNPs on survival." (PMID 38275875, 2024). "Expression of ProT and HOTAIR transcripts and their correlations in tumor tissues of bladder cancer patients and bladder cancer cell lines were determined by RT-qPCR." (PMID 36471329, 2022). "We demonstrate for the first time a critical role for HOTAIR and identify the involvement of the EGFR-ProT-NF-κB-HOTAIR signaling axis in cisplatin-induced cachexia in bladder cancer and likely other cancers." (PMID 36471329, 2022).